USP5 (ubiquitin specific peptidase 5)
Diseases named in the same sentence as USP5 in open-access papers (continued):
Sharing a sentence is not in itself a finding about the gene and the disease.
pancreatic cancer (continued). "Using different knockdown approaches, we show that expression of USP5 is essential for the proliferation and survival of pancreatic cancer cells, tested under different 2D and 3D cell culture conditions as well as in in vivo experiments." (PMID 29029505, 2017). "USP5 knockdown in pancreatic cancer cells leads to accumulation of polyubiquitinated proteins (Ub2-4), whereas monomeric ubiquitin (Ub) is diminished." (PMID 29029505, 2017). "Among the candidate genes identified in this screen was the deubiquitinase USP5, which subsequent gene expression analyses demonstrated to be significantly upregulated in primary human pancreatic cancer tissues." (PMID 29029505, 2017). "Consistent with its role as a deubiquinating enzyme, USP5 knockdown in pancreatic cancer cells led to accumulation of polyubiquitinated proteins (Ub2-4)." (PMID 29029505, 2017). "To assess the functional relevance of this upregulation of USP5, we transiently silenced USP5 gene expression using three different specific siRNAs in various pancreatic cancer cell lines." (PMID 29029505, 2017). "Taken together, our data support a novel important role for USP5 in maintenance of chromosomal integrity in pancreatic cancer." (PMID 29029505, 2017). "In this context, we performed a barcoded short hairpin RNA screen and identified the deubiquinating enzyme USP5 as a potential novel target gene in pancreatic cancer." (PMID 29029505, 2017). "A recent study confirmed that upregulated USP5 can promote pancreatic cancer." (PMID 33123271, 2020). "The effect of USP5 in progression and migration in pancreatic cancer has been confirmed, but its mechanism was still unknown." (PMID 33123271, 2020). "USP5 was also proved to mediate STAT3 signaling in pancreatic cancer cells." (PMID 33123271, 2020). "In conclusion, our study identifies that USP5 is highly expressed in pancreatic cancer and might have clinical significance for patients with pancreatic cancer." (PMID 33123271, 2020). "Results elucidated that USP5 contribute to cell invasion and metastasis in pancreatic cancer." (PMID 33123271, 2020). "Taken together, these results suggested that USP5 could evidently promote pancreatic cancer cells proliferation and metastasis." (PMID 33123271, 2020). "Small molecules inhibitor WP1130 29 and Chinese medicine Formononetin 6 were reported to inhibit USP5, which further indicated that targeting USP5 might be an effective strategy in pancreatic cancer treatment." (PMID 33123271, 2020). "In pancreatic cancer, the biological function of USP5, especially in migration and invasion remains unclear." (PMID 33123271, 2020). "We then determined whether USP5 mediates degrasyn‐induced degradation of WT1 protein in pancreatic cancer cells." (PMID 31845546, 2020). "In addition, studies have shown that USP5 is significantly up-regulated in pancreatic ductal adenocarcinoma (PDAC), and inhibition of USP5 can significantly reduce the growth of PDAC cells, suggesting that USP5 plays a vital role in the occurrence and development of pancreatic cancer." (PMID 36611139, 2023). "However, the role of USP5 in pancreatic cancer still needs to be studied." (PMID 33123271, 2020). "This study indicated that USP5 might be a potential target for the treatment of pancreatic cancer." (PMID 33123271, 2020). "Therefore, degrasyn might be a useful therapeutic agent for pancreatic cancer patients with high expressions of USP5 and WT1." (PMID 31845546, 2020). "Thus, USP5 may promote pancreatic cancer progression and metastasis through enhancing STAT3 signaling." (PMID 33123271, 2020). "Ubiquitin-specific peptidase 5 (USP5) correlates with serum CEA and CA19-9 levels in pancreatic cancer patients, and high USP5 expression is an unfavorable prognostic factor for pancreatic cancer." (PMID 36291659, 2022).
pancreatic cancer (continued). "Furthermore, USP5 is also found to contribute to the tumorigenesis and progression of many malignancies, including neuroblastoma, hepatocellular carcinoma, multiple myeloma, pancreatic carcinoma, ovarian cancer, colorectal cancer, and non-small cell lung cancer." (PMID 34483932, 2021). "Therefore, USP5 might be a potential novel target gene in pancreatic cancer." (PMID 33123271, 2020). "Thus, USP5 might be a potential target in pancreatic cancer treatment." (PMID 33123271, 2020). "Univariate analysis found that USP5 expression (P=0.001), tumor differentiation (P< 0.001), CEA level (P< 0.05) and CA19-9 level (P< 0.01) were significant prognostic predictors in pancreatic cancer." (PMID 33123271, 2020). "It was also reported that the aberrant activation of Wnt/β-catenin pathway, which is widespread in human cancers, including pancreatic cancer, favors the interaction between FOXM1 and USP5, thereby inducing FOXM1 protein stabilization and nuclear accumulation in glioma cells." (PMID 35241126, 2022). "In general, the results indicated that patients with negative USP5 expression have a longer survival time than those with positive USP5 expression in pancreatic cancer." (PMID 33123271, 2020). "For this purpose, the mRNA and protein expressions of USP5 were firstly detected in four pancreatic cancer cell lines and HPDE 6C7, a duct epithelial cell lines as normal control." (PMID 31845546, 2020). "The expression status and clinical significance of USP5 in pancreatic cancer has not been reported extensively." (PMID 33123271, 2020).
glioblastoma (12 papers, 2016 to 2023). The most malignant astrocytic tumor (WHO grade IV). "In glioblastoma multiforme, USP5 plays a critical role in tumorigenesis and progression by stabilizing CyclinD1 protein." (PMID 35895711, 2022). "Similarly, in a glioblastoma cell line, G9 decreased USP5 activity in a dose-dependent manner (right)." (PMID 31645897, 2019). "PTB is overexpressed in keloid tissues and fibroblasts, and as in glioblastoma, alternative splicing changes in RTN4 and USP5 by PTB have been observed." (PMID 37875914, 2023). "Another study reported that in glioblastoma, PTBP1 recognizes an alternative 5′ss within ubiquitin specific peptidase 5 (USP5) exon 15, resulting in the generation of USP5 isoform 2 with a shorter exon length." (PMID 37875914, 2023). "Similar results were obtained in a glioblastoma line (U87MG) with USP5 KD and TRAIL treatment, suggesting that USP5 can regulate the apoptotic response to TRAIL in resistant cell lines." (PMID 31645897, 2019).
non-small cell lung carcinoma (12 papers, 2019 to 2025). A group of at least three distinct histological types of lung cancer, including non-small cell squamous cell carcinoma, adenocarcinoma, and large cell carcinoma. "In non-small cell lung cancer, USP5 has been implicated in enhancing cellular proliferation and resistance to apoptosis by stabilizing PD-L1." (PMID 41213937, 2025). "For example, the USP5 inhibitor EOAI prevents non-small cell lung cancer progression by inducing DNA damage." (PMID 38217030, 2024). "In non-small-cell lung cancer and trophoblast cells, USP5 can deubiquitinate and stabilize β-catenin and activate the wnt/β-catenin signaling pathway." (PMID 37642235, 2023). "In non-small cell lung cancer, USP5 deubiquitinates β-catenin and leads to the activation of the β-catenin/c-Myc signaling pathway." (PMID 31371702, 2019). "In non-small cell lung cancer, USP5 promotes cell proliferation, colony formation and migration." (PMID 38229092, 2024). "For example, in breast cancer, USP5 promotes tumor progression by stabilizing HIF-2α, while in non-small cell lung cancer, USP5 enhances immune escape through PD-L1, promoting cancer development." (PMID 41213937, 2025).
myeloma (11 papers, 2017 to 2025). "MBZ, a broad-spectrum anthelmintic drug, not only transcriptionally inhibits USP5 expression in myeloma cells 28, but also has efficacy against different types of solid tumors 20-24, which is a repurposed drug for treating tumors." (PMID 39897046, 2025). "Previous study has indicated that mebendazole (MBZ) downregulates USP5 expression by suppressing USP5 transcription in myeloma cells." (PMID 39897046, 2025). "USP5 also deubiquitinates and stabilizes c-Maf, a transcription factor related to tumor and immune cell differentiation and suppresses apoptosis in multiple myeloma cells." (PMID 35895711, 2022). "USP5 deubiquitinates and stabilizes c-Maf, a transcription factor related to tumor and immune cell differentiation, and suppresses apoptosis in multiple myeloma cells." (PMID 33919439, 2021). "The ectopic expression of USP5 downregulates miR-125a mimic-induced apoptosis in multiple myeloma cells." (PMID 33919439, 2021). "Molecules targeting this pathway, such as Mebendazole, showed some potent anti-myeloma activity by inhibiting the USP5/c-Maf axis." (PMID 32117317, 2020). "The deubiquitinase USP5 stabilizes c-Maf, a key transcription factor in multiple myeloma (MM), but the mechanisms and significance are unclear." (PMID 28933784, 2017). "USP5 and OTUB1 stabilize c-Maf and promote myeloma cell proliferation and survival, which indicates that USP5/c-Maf or OTUB1/c-Maf axis could be a potential target for myeloma therapy." (PMID 34454635, 2021). "Recently, several reports demonstrated that inhibition of USP9X and/or USP5 by WP1130 leads to apoptotic cell death in malignant peripheral nerve sheath tumors and multiple myeloma." (PMID 30862047, 2019).
colorectal cancer (10 papers, 2020 to 2025). A primary or metastatic malignant neoplasm that affects the colon or rectum. "The transcription factor EBF1 enhances the transcription of USP5 in colorectal cancer cells by binding to its promoter." (PMID 39761299, 2025). "To this end, we subcutaneously transplanted the MC38 colorectal cancer cells into Usp5 WT and cKO C57BL/6J mice, which were treated with anti-PD-1 or control IgG." (PMID 37208329, 2023). "We subcutaneously transplanted the same number of MC38 colorectal cancer cells into WT and Usp5 cKO C57BL/6J mice." (PMID 37208329, 2023). "Our results showed that USP5 colocalized with PD-1 on tumor-infiltrating CD3+ T cells in human colorectal cancer samples." (PMID 37208329, 2023). "To further explore the clinical significance, we examined the protein expression of USP5 and PD-1 in tumor tissues of human colorectal cancer patients by using the multiplexed immunohistochemistry (mIHC) staining assay." (PMID 37208329, 2023). "USP5 is overexpressed in colorectal cancer tissues and promotes colorectal cancer cell proliferation and resistance to chemotherapeutics." (PMID 32477134, 2020). "Brigatinib triggers the apoptosis of colorectal cancer (CRC) cells via inducing ER stress mediated by oxysterol-binding protein-related protein 8 (ORP8)/ubiquitin-specific peptidase 5 (USP5), and protects ER stress through ER autophagy to optimize cancer treatment." (PMID 38262996, 2024). "By stabilizing Tu translation elongation factor, USP5 could regulate colorectal cancer cell growth." (PMID 33123271, 2020).
lung cancer (10 papers, 2021 to 2024). A malignant neoplasm involving the lung. "Here, we identified the deubiquitinase USP5, which is highly associated with stemness-related pathways in lung cancer specimens and critical for enhancing stemness properties and metastasis in lung cancer." (PMID 37726816, 2023). "Taken together, our results strongly suggest that USP5 expression is associated with cancer stemness and poor clinical outcomes in patients with lung cancer." (PMID 37726816, 2023). "Focusing on seven genes with deubiquitinase activity, we found that USP5 was the most significant candidate associated with poor overall survival in patients with lung cancer." (PMID 37726816, 2023). "We demonstrated that USP5 expression were positively correlated with the stemness-associated signatures and poor outcomes in lung cancer specimens." (PMID 37726816, 2023). "Here, our findings provide new insights indicating that USP5 interacts with β-catenin, causes β-catenin deubiquitination, prolongs the β-catenin protein half-life, and thus increases the expression of Wnt/β-catenin downstream target genes in lung cancer." (PMID 37726816, 2023). "The data support an association between USP5 and CSCs in lung cancer." (PMID 37726816, 2023). "While trying to comprehensively understand the association between USP5 and the clinical outcomes of lung cancer patients, we first found significantly increased expression of USP5 in human LUAD samples (n = 509) compared to normal tissue samples (n = 59) in the TCGA-LUAD dataset." (PMID 37726816, 2023). "For instance, USP5 deubiquitinates and stabilizes the immunosuppressive molecule PD‐L1, thereby promoting the progression of lung cancer." (PMID 39143031, 2024). "In this study, we observed that the expression of USP5 promoted the progression of lung cancer cells by the mTOR signaling pathway and interacted with PARP1." (PMID 37060095, 2023). "It was observed that the levels of USP5 protein in lung cancer tissue were up-regulated than in corresponding paracancerous tissues." (PMID 37060095, 2023). "Altogether, these data support our clinical findings, and we have identified a new role for USP5 in regulating stemness properties in lung cancer." (PMID 37726816, 2023). "This work is also the first study to show a correlation between a stemness index and USP5 expression in lung cancer patients." (PMID 37726816, 2023). "In summary, our work demonstrates that USP5 promotes β-catenin stabilization and Wnt signaling activation to control cancer stemness and metastasis in lung cancer." (PMID 37726816, 2023). "After the knockdown of PARP1, the effect of USP5-dependant progression in lung cancer cells will be terminated." (PMID 37060095, 2023). "For this cohort, 28% of the lung cancer cases exhibited high levels of USP5 expression/Wnt signaling/stemness, while 25.6% of the lung cancer cancers had low levels." (PMID 37726816, 2023). "Taken together, these results indicated that mTOR signaling is the upstream of USP5 and regulated the expression of USP5 in lung cancer." (PMID 37060095, 2023). "Overall, our data suggest that USP5 is a potential target that is highly correlated with stemness activities in lung cancer." (PMID 37726816, 2023). "Accordingly, expression of USP5 was positively correlated with the enrichment score of the Wnt/TCF pathway signature in human lung cancer." (PMID 37726816, 2023). "In the cohorts analyzed in this study, 24.6% of the lung cancer cases exhibited high levels of USP5 expression/Wnt signaling/stemness, while 23.4% of the lung cancer cases had low levels, indicating that this pathway exists in patients with lung cancer." (PMID 37726816, 2023). "To determine the role of USP5 in lung cancer development, we first evaluated the USP5 expression in lung cancer based TCGA database." (PMID 37060095, 2023).
lung cancer (continued). "Collectively, these data suggest that USP5 deubiquitinates β-catenin, promotes β-catenin stability, and subsequently promotes Wnt signaling pathway activity in lung cancer cells." (PMID 37726816, 2023). "Overall, our data suggest that high levels of USP5 expression/Wnt signaling/stemness predict poor overall survival in lung cancer." (PMID 37726816, 2023). "Collectively, these results show that USP5 plays an important role in maintaining stemness properties in lung cancer." (PMID 37726816, 2023). "In the study, it was observed that the level of USP5 protein in lung cancer tissues was higher than in the corresponding paracancerous tissues." (PMID 37060095, 2023). "Our clinical analysis not only indicates the existence of a significant association between the deubiquitination process and a stemness index but also identifies USP5 as the important factor controlling stem-like properties in lung cancer." (PMID 37726816, 2023). "Taking together, these in vivo results confirmed that USP5 promotes lung cancer growth through regulating PD-L1 stability." (PMID 34741014, 2021). "Notably, USP5 knockdown in a Lewis lung carcinoma mouse model resulted in reduced tumor growth, emphasizing USP5’s role in PD-L1 regulation and the promotion of lung cancer progression." (PMID 38474186, 2024). "The USP5 levels are detected in lung cancerous and paracancerous tissue by quantitative real-time polymerase chain reaction (qRT-PCR) and Western blotting methods to explore their roles in lung cancer progression." (PMID 37060095, 2023). "Together, we believe that eliminating the effect of USP5 could delay the progression of lung cancer, becoming a potential target for lung cancer treatment." (PMID 37060095, 2023). "In summary, it was observed that the USP5 was highly expressed in lung cancer tissues." (PMID 37060095, 2023). "Furthermore, USP5 expression was shown to be positively correlated with mRNAsi, suggesting a connection between USP5 and CSCs in lung cancer." (PMID 37726816, 2023). "Interestingly, the increased expression levels of USP5 protein had significantly promoted the progression of lung cancer cells by the mTOR signaling pathway and interacted with PARP1." (PMID 37060095, 2023). "Moreover, we found ubiquitin-specific peptidase 5 (USP5) to be the most significant candidate correlated with both the mRNAsi and poor overall survival in lung cancer." (PMID 37726816, 2023). "Notably, USP5 is highly expressed in lung cancer, USP5 overexpression promoted the proliferation and migration in the lung cancer cell lines, H1299 and A549, while knockdown of USP5 inhibited these via regulating the PARP1-mediated mTOR signaling pathway." (PMID 37060095, 2023). "We next examined the role of USP5 in regulating the metastasis of lung cancer cells." (PMID 37726816, 2023). "Further, flow cytometry experiments are performed to examine the effect of USP5 on lung cancer." (PMID 37060095, 2023). "Altogether, this study indicates that targeting USP5 with small molecules in these patients may have beneficial effects that improve future lung cancer therapeutics." (PMID 37726816, 2023). "Taken together, these results indicated that USP5 possesses oncogenic activities in lung cancer." (PMID 37060095, 2023). "Since β-catenin stability is tightly controlled by ubiquitination-dependent degradation, we wondered whether USP5 regulates the deubiquitination and stability of β-catenin in lung cancer." (PMID 37726816, 2023).